PAX8 (paired box 8)
Diseases named in the same sentence as PAX8 in open-access papers (continued):
Sharing a sentence is not in itself a finding about the gene and the disease.
endometrial tumors (1 paper, 2020). "Since these endometrial tumors are negative or weakly positive for hormone receptors, immunostaining for PAX8 is more helpful for obtaining an accurate diagnosis." (PMID 32164210, 2020).
Endometrioid carcinoma of the fallopian tube (1 paper, 2025). "Endometrioid carcinoma of the fallopian tube can closely mimic FATPWO, particularly when PAX8 and CK7 are both negative." (PMID 40959354, 2025).
endometrium adenocarcinoma (1 paper, 2020). An adenocarcinoma arising from the uterine body cavity. "While 9/11 (81.8%) of the endometrium adenocarcinoma were found positive for the PAX-8 expression." (PMID 32847623, 2020). "Besides that, the lack of PAX-8 expression among those who were diagnosed with well differentiated SCC and metastatic adenocarcinoma could play a significant role in either gynecologic cancer differentiation or in detection of endometrium adenocarcinoma progression to metastatic adenocarcinoma." (PMID 32847623, 2020).
glomerular disease (1 paper, 2014). "Our finding demonstrates that this master regulator of renal development is expressed in rat PECs (arrows) and is consistent with our previous report showing increased expression of Pax8 during a murine model of glomerular disease." (PMID 25127402, 2014).
hemangioblastoma (1 paper, 2022). "The diagnosis of hemangioblastoma was confirmed by positive immunostaining for alpha-inhibin, S100, neuron-specific enolase, and PAX8." (PMID 35220972, 2022). "The majority of renal hemangioblastomas showed positive immunostaining for PAX8, which supports the idea that the immunoprofiles of extraneuraxial hemangioblastomas can vary depending on sites of origin." (PMID 35220972, 2022). "From our review cases and the present case, we have found that the majority of renal hemangioblastomas showed positive immunostaining for PAX8, which supports the idea that the immunoprofile of extraneuraxial hemangioblastomas can vary depending on sites of origin." (PMID 35220972, 2022). "In those reported cases, the tumor cells expressed alpha-inhibin and S100 in the hemangioblastoma-like part only (not in the clear cell RCC part), but PAX8, CD10, and RCC were positive in both components of the tumor." (PMID 35220972, 2022).
Hypoglycemia (1 paper, 2019). A decreased concentration of glucose in the blood. "Pax8 -/- mice displayed lower body and tissue weights, reduced food intake and hypoglycemia that result in peri-weaning death (χ2 ≥ 100 and P < 0.0001 vs. Wt)." (PMID 31518338, 2019).
idiopathic pulmonary fibrosis (1 paper, 2020). Idiopathic pulmonary fibrosis (IPF) is a nonneoplastic pulmonary disease that is characterized by the formation of scar tissue within the lungs in the absence of any known cause. "pax8 is overexpressed in idiopathic pulmonary fibrosis (IPF) fibroblasts, which suggests that it may be a regulator in promoting the growth, survival, and proliferation of fibroblasts." (PMID 33193637, 2020).
invasive carcinoma (1 paper, 2025). A carcinoma that is not confined to the epithelium, and has spread to the surrounding stroma. "Some markers of tubal differentiation present in the endosalpingiosis such as tubulin and OVGP1 are diminished in the invasive carcinoma, which retains expression of WT1, PAX8." (PMID 40940856, 2025).
jejunal adenocarcinoma (1 paper, 2026). A adenocarcinoma that involves the jejunum. "Immunohistochemical analysis demonstrated CK7 positivity, CK20 positivity, CDX2 positivity, and PAX8 negativity in both ovarian and jejunal specimens, confirming a diagnosis of primary jejunal adenocarcinoma with ovarian metastasis." (PMID 42083706, 2026).
kidney injury (1 paper, 2022). Trauma to the kidney. "Additionally, we analyzed renal expression of PAX8 in experimental model of postischemic acute kidney injury in Wistar and spontaneously hypertensive (SHR) rats." (PMID 36140438, 2022).
large cell carcinoma (1 paper, 2014). A malignant epithelial neoplasm composed of large, atypical cells. "In adeno carcinoma, almost 20% cases were PAX8- nonexpressors, whereas in large cell carcinoma, only 6-7% of the cases were negative for PAX8 expression." (PMID 24628993, 2014).
medulloblastoma (1 paper, 2022). A malignant, invasive embryonal neoplasm arising from the cerebellum. "Interestingly, PAX8 expression in medulloblastoma was an independent marker of good prognosis, and PAX8 knockdown reduced proliferation, a reverse role compared to its known role in Müllerian tumors." (PMID 35806410, 2022).
mesenchymal tumors (1 paper, 2024). "While PAX8 is generally negative in mesenchymal tumors, high-grade RCCs with sarcomatoid change may retain PAX8 positivity." (PMID 38297323, 2024).
mesonephric adenocarcinoma (1 paper, 2019). An adenocarcinoma of the cervix or the vagina arising from mesonephric remnants. "Immunohistochemically, mesonephric adenocarcinoma is usually diffusely and strongly positive for CD10 (apical and luminal), CK7, PAX8, EMA (epithelial membrane antigen), and vimentin." (PMID 31266530, 2019).
MRKH syndrome (1 paper, 2021). "In cases of MRKH syndrome, recurrent microdeletions and microduplications (1q21,1; 2q12.1q14.1; 16p11.2; 17p14.3; 17q12; 22q11.21; 22q11.21q11.23) and mutations in genes located on these loci (RBM8A, PAX8, TBX1, TBX6, LHX, HNF1B, WNT4) have been identified." (PMID 33883018, 2021).
mucinous cystadenocarcinoma (1 paper, 2019). An invasive adenocarcinoma characterized by cystic changes and the presence of malignant glandular cells which contain intracytoplasmic mucin. "All malignant mucinous cystadenocarcinomas (7/7; 100%) expressed CK7, and were negative for PAX8 and SATB2." (PMID 31771640, 2019).
Nephropathy (1 paper, 2022). A nonspecific term referring to disease or damage of the kidneys. "Actually, in patients with AKI of unknown etiology, the structure of renal tissue was almost normal and we can assume that the intensity of kidney damage was not enough stimulus to initiate PAX8 re-expression." (PMID 36140438, 2022). "Presence, location and extent of PAX8 expression were analyzed among 31 human kidney samples of AKI (25 autopsy cases, 5 kidney biopsies with unknown etiology and 1 AKI with confirmed myoglobin cast nephropathy), as well as in animals with induced postischemic AKI." (PMID 36140438, 2022).
nephrotic syndrome (1 paper, 2022). A collection of symptoms that include severe edema, proteinuria, and hypoalbuminemia; it is indicative of renal dysfunction. "Nevertheless, mostly in patients with nephrotic syndrome, atrophic renal tubular epithelial cells regardless of nephronic segments, as well as non-atrophic proximal tubular epithelial cells close to the area of renal interstitial fibrosis, expressed PAX8 in the nuclei." (PMID 36140438, 2022).
nodular goiter (1 paper, 2016). Goiter characterized by discrete tissue mass(es) that may or may not produce thyroid hormones. "Upregulation of TSHR, TTF-1, and PAX8 is associated with low follicular lumen iodine content in nodular goiter." (PMID 27525008, 2016). "Western blot immunohistochemistry was performed to assay TSHR, TTF-1, and PAX8 in thyrocytes of nodular goiter as well as in extranodular normal thyroid tissues." (PMID 27525008, 2016). "Immunohistochemistry was also performed to determine TSHR, TTF-1, and PAX8 expression in 30 nodular goiter and 30 control thyroid samples." (PMID 27525008, 2016). "The Spearman rank coefficient was performed to determine the correlation among the parameters of TSHR, TTF-1, PAX8, and iodine in 30 nodular goiter and control samples." (PMID 27525008, 2016). "TTF-1 and PAX8 were confined to the nucleus of the thyrocytes, and both types of immune reactivity in nodular goiter were significantly higher than those in the control." (PMID 27525008, 2016). "The current study showed that low iodine status in nodular goiter was associated with high levels of expression of TTF-1 and PAX8." (PMID 27525008, 2016). "in addition to the increase in TSHR expression, the expressions of TTF-1 and PAX8 in nodular goiter lesions were also significantly higher than those in control tissues." (PMID 27525008, 2016). "Western blot was performed to determine the expression of TSHR, TTF-1, and PAX8 in 10 nodular goiter and 10 control thyroid samples." (PMID 27525008, 2016). "TSHR expression in nodular goiter lesions may be associated with upregulated expression of transcription factors TTF-1 and PAX8." (PMID 27525008, 2016). "The TSHR, TTF-1, and PAX8 in nodular goiter were significantly higher than those in the controls." (PMID 27525008, 2016). "Results showed that, in addition to the increase in TSHR expression, nodular goiter lesions also expressed significantly more TTF-1 and PAX8 than normal thyroid tissues." (PMID 27525008, 2016).
NUT carcinomas (1 paper, 2022). "Two of the three cases showed characteristic histologic features of NUT carcinoma, of which one also expressed PAX8 in addition to diffuse p63 by immunohistochemistry." (PMID 34997561, 2022).
osteoarthritis (1 paper, 2021). A noninflammatory degenerative joint disease occurring chiefly in older persons, characterized by degeneration of the articular cartilage, hypertrophy of bone at the margins and changes in the synovial membrane. "PAX8 has been reported to be hypomethylated in human cartilage in individuals with osteoarthritis, which is of interest considering our finding that low PAX8 methylation is associated with higher free T4, which, in turn, is associated with lower BMD." (PMID 34739318, 2021).
ovarian carcinosarcoma (1 paper, 2022). A highly aggressive malignant neoplasm arising from the ovary.
ovarian clear cell neoplasms (1 paper, 2025). "The tumor cell expression of HNF1-β and PAX-8 serves as a highly specific immunomarker combination for ovarian clear cell neoplasms, providing cornerstone evidence for the diagnosis." (PMID 41479789, 2025).
penile carcinoma (1 paper, 2026). "Immunohistochemistry demonstrated diffuse p40 and p63 positivity with PAX8 and p16 negativity, supporting a urothelial tract origin rather than a primary penile carcinoma." (PMID 41836245, 2026).
peritoneal disease (1 paper, 2015). "Despite fewer sites of dissemination, animals with peritoneal disease had tumors in their ovaries, with infiltration noted via CK8 and PAX8 positive tumor cells engulfing the ovaries and leaving follicular structures surrounded by MOE-derived tumors." (PMID 25971410, 2015).
pituitary (1 paper, 2021). "In this study, we found somatic mutations in SETD2 and PAX8, which are known tumor-related genes but not reported in tumors of the posterior pituitary." (PMID 34925233, 2021).
pseudomyxoma peritonei (1 paper, 2023). An appendix cancer that is characterized by progressive accumulation of mucus-secreting tumor cells within the abdomen and pelvis. "AGN343 patient had a pseudomyxoma peritonei (CK7 − /CK20 score 3 + /CDX2 score 3/SABT2 score 1, and ER − /PAX8 − /WT1 −); she underwent right and transversal colectomy during debulking, but neither primary cancers nor polyps were identified." (PMID 36346458, 2023).
rhabdoid tumor (1 paper, 2023). An aggressive malignant embryonal neoplasm usually occurring during childhood. "In summary, PAX8 inhibition-resistant ccRCC cells display a global reduction in the kidney-specific cis-regulatory and transcriptional programs in favor of a dedifferentiated state which shares molecular features of SMARCB1 loss in pediatric rhabdoid tumors." (PMID 37554444, 2023).
spindle cell neoplasm (1 paper, 2018). A benign or malignant neoplasm characterized by the presence of neoplastic spindle cells. "CT-guided core biopsy was positive for high-grade spindle cell neoplasm (positive for smooth muscle actin, desmin, S100, and CD31; negative for CD34, PAX8, and beta-catenin) and verified by two independent pathologists." (PMID 30558620, 2018). "CT-guided core biopsy was positive for high-grade spindle cell neoplasm (positive for smooth muscle actin, desmin, S100, and CD31; negative for CD34, PAX8, and beta-catenin)." (PMID 30558620, 2018).
squamous cell lung carcinoma (1 paper, 2016). A carcinoma arising from squamous bronchial epithelial cells. "Elevated levels of PAX8 have been seen in several tumor types and epigenetic silencing has been observed in squamous cell lung cancer." (PMID 26963385, 2016).
thymic epithelial neoplasm (1 paper, 2021). An epithelial neoplasm that affects the thymus gland. "PAX8 is expressed in epithelial tumors in different organs, as well as in thymic epithelial neoplasms." (PMID 34540435, 2021). "Moreover, PAX8 is utilized to differentiate thymic epithelial neoplasms from other pulmonary and mediastinal epithelial masses." (PMID 34540435, 2021).
thymoma (1 paper, 2021). A neoplasm arising from the epithelial cells of the thymus. "Seventy-seven percent of thymic cancers, 93% of WHO type B thymomas, and 100% of WHO type A thymomas showed positive PAX8 immunoreactivity." (PMID 34540435, 2021). "In yet another study, PAX8 immunoreactivity was assessed in 31 thymic carcinomas, 30 patients with World Health Organization (WHO) type B thymoma, and 30 patients with WHO type A thymomas." (PMID 34540435, 2021).
thyroid angiosarcomas (1 paper, 2024). "By immunohistochemistry, thyroid angiosarcomas are strongly and diffusely positive for pan-endothelial markers, i.e., CD31, CD34, FLI-1 and ERG, but lack expression of thyroid-related immunomarkers including thyroglobulin, TTF1 and PAX8." (PMID 39422760, 2024).
thyrotoxicosis (1 paper, 2011). A hypermetabolic syndrome caused by the elevation of thyroid hormone levels in the serum. "This is compatible with the recent report comparing Pax8-null mice with Pax8/TRH-R1 double knockout mice and the previous study that administration of TRH failed to stimulate TSHβ synthesis in a subject with overt thyrotoxicosis." (PMID 21533184, 2011).
urothelial cell carcinoma (1 paper, 2023). "Furthermore, the positivity reaction for PAX8, excluded the poorly differentiated urothelial cell carcinoma." (PMID 37495956, 2023).
vascular neoplasm (1 paper, 2025). A benign, intermediate, or malignant neoplasm arising from vascular tissue including arteries, veins, venous sinuses, lymphatic vessels, arterioles and capillaries. "In our case, immunoreactivity for GATA3, estrogen, and progesterone receptors confirmed the breast tissue origin, while negative PAX8 and ERG stains ruled out Müllerian origin and vascular neoplasms, respectively." (PMID 41393763, 2025).
Waardenburg syndrome (1 paper, 2022). A disorder characterized by varying degrees of deafness and minor defects in structures arising from neural crest, including pigmentation anomalies of eyes, hair, and skin. "Six new genes were associated with NSHI: INPP4B, CCDC141, MYO19, DNAH11, SOX9, and POTEI; and one new gene, PAX8, was associated with Waardenburg syndrome." (PMID 35440622, 2022). "A variant in a candidate gene [PAX8: c.968C>G: p.(P323R)] was found in one of the two families clinically presenting with Waardenburg syndrome." (PMID 35440622, 2022).
tumor (382 papers, 2004 to 2026). "PAX8 encodes a transcription factor associated with embryogenesis and tumor development, and its expression has been confirmed in the thyroid, kidney, brain, and Müllerian-derived tissues, including the fallopian tubes." (PMID 41041096, 2025). "Rhabdoid tumor cells frequently exhibit partial loss of renal epithelial markers such as PAX8 and Claudin4 while generally retaining the expression of cytokeratin AE1/AE3 and the hypoxia-associated marker CAIX." (PMID 40940841, 2025). "We assessed the expression of TIM-3 by tumor cells – defined as pancytokeratin and/or PAX8 positive cells—and tested its association with plasma sTIM-3 in a subset of BIONIKK participants (n = 22)." (PMID 39953623, 2025). "PAX8 has been implicated in regulating the tumor microenvironment by enhancing fibronectin and collagen expression while increasing TGF-β1 secretion." (PMID 38928435, 2024). "We find that PAX8 inhibition resistance in ccRCC cells is associated with a dramatic change in tumor histology with acquired features of morphological neuroendocrine differentiation, a phenotype not commonly seen in adult renal tumors." (PMID 37554444, 2023). "PAX8 deficiency in HGSC cells can cause cellular tumor death and decreases invasion and cell migration." (PMID 37891636, 2023). "Resistance to PAX8 suppression can be achieved through multiple routes and it is linked to dedifferentiation, a dramatically altered tumor morphology and acquired dependencies on previously dispensable transcriptional regulators." (PMID 37554444, 2023). "Organ-specific mimetism has the potential to affect the expression of known markers associated with the primary tumour of origin, thus partially explaining the low PAX8 expression levels detected in the CTCs from the OC cases used in the current research." (PMID 34944844, 2021). "The WT1-wild-type tumours show a closer phenotypic resemblance to the effects of the post-MET Pax8+/Cre-mediated loss of Wt1, even though the initiating genetic event will be different for these tumours." (PMID 26035382, 2015). "A reduction of the PAX8 expression levels in low-grade tumours is consistent with the association of PAX8 expression with more aggressive tumours." (PMID 24602166, 2014). "To distinguish cancer cells from non-cancerous cells in the organoids and the stromal cell cultures, respectively, we used established tumor marker genes, including PAX8, MUC16 (encoding CA-125) and EPCAM, collectively referred to as PAX8+ cells (Online “Methods”, Suppl." (PMID 39362905, 2024). "Immunohistochemistry for the tumour markers Pax8 and WT1, commonly associated with EOC and HGSOC18, was performed to determine the tumour cell load in tissues and demonstrated the presence of micro-metastasis of tumour cells in some of the macroscopically non-cancerous tissues measured." (PMID 30279418, 2018). "In addition, low PAX8 expression may partly be explained by the downregulation or total loss of tumour markers with time in the circulatory system." (PMID 34944844, 2021). "PAX3, PAX5, and PAX8 are mainly associated with immune checkpoint expression, including PD-L1 and TIGIT, while PAX6 is linked to microsatellite instability and tumor mutational burden, implicating it in genomic dysregulation." (PMID 41752124, 2026). "The tumor cells showed expression of PAX8, CA9, AMACR/P504S, Vimentin, CK7, CD10, FH, INI1(SMARCB1) and ELOC(TCEB1), and ELOC was mainly located in the nucleus." (PMID 41306531, 2025).